ZNF496 (zinc finger protein 496)
Description:
DNA-binding transcription factor that can both act as an activator and a repressor.
Synonyms: ZKSCAN17; MGC15548; ZSCAN49; NIZP1; ZFP496
Tractability: PROTAC: UniProt records ubiquitination sites on it; ubiquitination databases record sites on it.
Gene: Protein-coding gene on chromosome 1 (247,297,412 to 247,332,822, reverse strand). Ensembl gene ENSG00000162714.
Subcellular location: Nucleus
Subcellular location (Human Protein Atlas): Nucleoplasm; Cytosol
Pathways (Reactome):
Gene expression (Transcription): Generic Transcription Pathway
Gene Ontology:
Molecular function: protein binding; DNA binding; DNA-binding transcription factor activity, RNA polymerase II-specific; RNA polymerase II cis-regulatory region sequence-specific DNA binding
Biological process: positive regulation of DNA-templated transcription; regulation of transcription by RNA polymerase II; regulation of DNA-templated transcription
Cellular component: nucleus
Genetic constraint (gnomAD): Loss-of-function variants: 11 observed, 60.69 expected, observed/expected ratio (o/e) 0.18, 90% interval 0.11 to 0.3. The upper end of that interval is the gene's LOEUF score, 0.3, which puts it in group 1 of 6, group 1 being the genes least tolerant of losing a copy. Missense variants: 660 observed, 811.46 expected, observed/expected ratio (o/e) 0.81, 90% interval 0.76 to 0.87. Synonymous variants: 338 observed, 330.86 expected, observed/expected ratio (o/e) 1.02, 90% interval 0.93 to 1.12.
Homologues: Orthologues: chimpanzee ZNF496 (99% identical), macaque ZNF496 (97% identical), pig ZNF496 (84% identical), mouse Zkscan17 (78% identical), rat Zfp496 (76% identical), dog ZNF496 (62% identical), Drosophila melanogaster CG12391 (13% identical), Drosophila melanogaster hb (12% identical), zebrafish plagl2 (9% identical), zebrafish ovol1a (9% identical), Caenorhabditis elegans hbl-1 (8% identical), zebrafish ovol1b (8% identical), and 3 more. Paralogues in human: ZNF18 (28% identical), ZSCAN29 (28% identical), ZKSCAN2 (27% identical), ZNF202 (27% identical), ZSCAN32 (25% identical), ZNF274 (22% identical), ZNF446 (20% identical), ZSCAN18 (19% identical), ZSCAN5B (19% identical), ZSCAN5C (19% identical), ZNF174 (19% identical), ZSCAN5A (18% identical), and 17 more.
Diseases named in the same sentence as ZNF496 in open-access papers:
ZNF496 is named in the same sentence as 13 diseases in open-access papers, as found by Europe PMC text mining. Sharing a sentence is not in itself a finding about the gene and the disease. The quoted sentences say what the papers report.
breast carcinoma (2 papers, 2021). "As for ZNF496, a recent report demonstrates that it acts as a target gene-specific ERα corepressor and inhibits the growth of breast cancer, suppressing the development of ERα-positive tumors." (PMID 34638319, 2021). "Second, ZNF496, as a mediating gene related to BRCA, was shown to significantly suppress ERα transactivation through over-expression, reduce the expression of estrogen receptor-alpha specific target genes, and inhibit the growth of breast cancer cells via ERα in an E2-dependent manner." (PMID 34464378, 2021).
developmental delay (1 paper, 2025). "As documented, ZNF496 interacts with JARID2, a gene linked to developmental delay, intellectual disability, and facial dysmorphism (MIM phenotype entry number #620098)." (PMID 40806714, 2025).
diabetic nephropathy (1 paper, 2025). "Additionally, it is interesting to note the ZNF496 gene, which, according to single-cell sequencing data, is one of the main regulators that promote diabetic nephropathy." (PMID 41465472, 2025).
Hypertension (1 paper, 2014). The presence of chronic increased pressure in the systemic arterial system. "In particular, ZNF496 is associated with preeclampsia (ie, hypertension during pregnancy) and malignant pheochromocytoma tumors, which can lead to malignant hypertension." (PMID 25519321, 2014).
cancer (2 papers, 2021). A tumor composed of atypical neoplastic, often pleomorphic cells that invade other tissues. "Our data strongly suggest that ZNF420 and ZNF496 are both involved in KIRC progression as tumor suppressors, as their upregulation corresponds to better patient survival and lower tumor grade followed by a significant depletion of cancer stemness characteristics." (PMID 34638319, 2021).
neurodevelopmental disorder (1 paper, 2025). A behavioral and cognitive disorder with onset during the developmental period that involves impaired or aberrant development of intellectual, motor, or social functions. "The purpose of this work is to associate the ZNF496 gene with the neurodevelopmental disorder observed in the patient’s clinical examination." (PMID 40806714, 2025). "ZNF496 encodes a C2H2-type zinc finger protein, a family frequently implicated in neurodevelopmental disorders." (PMID 40806714, 2025).
ZNF496 also shares sentences with these, for which no sentence is quoted: tumor (2 papers); ciliopathy (1); Intellectual disability (1); malignant hypertension (1); Obesity (1); preeclampsia (1); schizophrenia (1).